TUBB3 (tubulin beta 3 class III)
Diseases named in the same sentence as TUBB3 in open-access papers (continued):
Sharing a sentence is not in itself a finding about the gene and the disease.
Facial palsy (3 papers, 2020 to 2023). Facial nerve palsy is a dysfunction of cranial nerve VII (the facial nerve) that results in inability to control facial muscles on the affected side with weakness of the muscles of facial expression and eye closure. "Mutations in TUBB3 were previously reported in facial palsy and peripheral neuropathy and also reported in the development of gallbladder cancers through Akt/mTOR signal pathway." (PMID 37466845, 2023). "The TUBB3 E421 residue is the third kinesin interaction site to be altered in CFEOM, and the resulting E421D syndrome can include CFEOM, mild learning difficulty, facial nerve palsy, focal cortical dysplasia and mild ataxia." (PMID 31302631, 2020).
hepatocellular carcinoma (3 papers, 2018 to 2024). A malignant tumor that arises from hepatocytes. "Downregulating TUBB3 by AC10364 suppressed cell viability and proliferation in hepatocellular carcinoma." (PMID 35173149, 2022).
Intellectual disability (3 papers, 2021 to 2023). "TUBB3 R46G [136C > G]: A de novo variant in a microcephalic 2-year-old girl with intellectual disability and motor delays." (PMID 37600020, 2023). "Consistent with milder findings by MRI, while TUBB3-MCDs can result in intellectual disabilities, ASD, and seizures, some individuals have very mild phenotypes." (PMID 37600020, 2023). "The recently reported KIF21A L685P substitution results in a syndromic CFEOM human phenotype that is very similar to the syndromic TUBB3-CFEOM phenotypes, with facial weakness, progressive axonal polyneuropathy, and intellectual disability in addition to CFEOM." (PMID 37600020, 2023).
microlissencephaly (3 papers, 2014 to 2022). Microlissencephaly describes a heterogenous group of a rare cortical malformations characterized by lissencephaly in combination with severe congenital microcephaly, presenting with spasticity, severe developmental delay, and seizures and with survival varying from days to years. "In this cohort, TUBA1A mutations represent the major cause of microlissencephaly, although TUBB2B and TUBB3 mutations may also be found." (PMID 25059107, 2014). "Because of the potential implications for the genetic screening, our data together with these observations imply that microlissencephaly must be distinguished from LCH, the former being related to either TUBA1A, TUBB2B or TUBB3 mutations, while the latter strongly related to TUBA1A mutations." (PMID 25059107, 2014).
ovarian tumors (3 papers, 2013 to 2023). "TUBB3 RNA was up-regulated in 10 of 17 (59%) new ovarian tumors." (PMID 28090373, 2016).
Parkinson disease (3 papers, 2022 to 2025). A progressive degenerative disorder of the central nervous system characterized by loss of dopamine producing neurons in the substantia nigra and the presence of Lewy bodies in the substantia nigra and locus coeruleus. "Noteworthy, TH, dopamine receptor 2 (DRD2), SLC6A3/DAT, SLC18A2, tubulin beta 2A (TUBB2A), tubulin alpha 4A (TUBA4A), and tubulin beta 3 (TUBB3) were the 7 key genes enriched in the Parkinson disease pathway." (PMID 40259945, 2025).
viral infection (3 papers, 2018 to 2024). "Costaining of NP with neuronal markers TUBB3 (immature) and OMP (mature) revealed viral infection in a subset of cells from the neuronal lineage in the basal half of epithelium." (PMID 38483537, 2024). "When BrdU was administrated prior to the ASCL1 virus infection, most of the non-converted TUBB3-negative cells in BrdU/GM group and the converted TUBB3-positive neurons were labeled by BrdU." (PMID 31212628, 2019).
developmental delay (2 papers, 2021 to 2024). "Patients with TUBB3 p.Arg262His and p.Asp417His mutations present with CFEOM, CFP, developmental delay, progressive sensorimotor polyneuropathy, and congenital joint contractures." (PMID 33827624, 2021).
endometrial cancer (2 papers, 2013 to 2014). Primary or metastatic malignant neoplasm involving the endometrium (mucous membrane that lines the endometrial cavity). "Recent studies demonstrated that TUBB3 expression is indeed modulated by miR-200c in Hey cells and in Hec50 endometrial cancer cells." (PMID 23394580, 2013). "Regarding miRNA potentially affecting the drug target, TUBB3 has been unraveled as a target for miR-200c in ovarian and endometrial cancer cells, and the ectopic expression of this miRNA downregulated TUBB3 and enhanced sensitivity to microtubule-targeting agents, including paclitaxel." (PMID 25250326, 2014).
esophageal adenocarcinoma (2 papers, 2017 to 2018). A malignant tumor with glandular differentiation arising predominantly from Barrett mucosa in the lower third of the esophagus. "Immunohistochemical TUBB3 status reveals differences between gastric and esophageal adenocarcinoma in a small cohort of 126 and 106 tumor samples respectively." (PMID 29383151, 2017). "This study investigated 106 esophageal adenocarcinomas and was able to detect TUBB3 protein in 32,1% of these tumors." (PMID 29383151, 2017). "TUBB3 serves as an independent prognostic marker and may be a valuable biomarker for routine application in esophageal adenocarcinoma especially to address the need for adjuvant treatment in individuals following neoadjuvant therapy and surgery." (PMID 29383151, 2017). "Our results suggest that TUBB3 may be a valuable prognostic marker for routine application in adenocarcinoma of the esophagus, especially to address the need for adjuvant treatment in individuals following neoadjuvant therapy and surgery." (PMID 29383151, 2017). "Our study emphasized the significant importance of TUBB3 in esophageal adenocarcinoma." (PMID 29383151, 2017).
esophageal cancer (2 papers, 2014 to 2020). A primary or metastatic malignant neoplasm involving the esophagus. "The expression levels of ERCC1, TYMS, TUBB3, RRM1 and TOP2A were determined using a microarray technique, while Spearman’s rank correlation analysis was used to determine the strength of the correlations between the expression levels of the biomarkers and the pathogenesis of esophageal cancer." (PMID 24926347, 2014).
fibrosis (2 papers, 2017 to 2021). the formation of excess fibrous connective tissue in an organ or tissue in a reparative or reactive process. "Variants in the TUBB3 gene, one of the tubulin-encoding genes, are known to cause congenital fibrosis of the extraocular muscles type 3 and/or malformations of cortical development." (PMID 33921132, 2021). "In one of the five patients not meeting the diagnostic criteria the genetic testing revealed a TUBB3 mutation, causing congenital fibrosis of the extraocular muscles type 3, which is an alternative diagnosis also found in other studies." (PMID 28061881, 2017).
glaucoma (2 papers, 2013 to 2024). Increased pressure in the eyeball due to obstruction of the outflow of aqueous humor. "In a rat glaucoma model, it was demonstrated that while the number of RGCs declined during the progression of glaucoma, the overall level of TUBB3 protein remained elevated." (PMID 39318470, 2024). "The authors of the study were able to detect the expression of TUBB3 in desmin-, PDGFR-β- and α-SMA-positive pericytes, as well as in endothelin-1-positive endothelial cells in eyes affected by glaucoma." (PMID 39318470, 2024). "We hypothesized that beta III-tubulin (TUBB3) expression in the retinal endothelial cells of the retina might be increased during the development of EAU, similar to recent findings in a glaucoma model." (PMID 39318470, 2024). "Therefore, to determine the extent of RGC somal loss in D2.C5B6 mice, retinal flat mounts from D2.C5B6 and D2 eyes with no detectable glaucoma (NOE) and severe glaucoma were labeled with TUBB3, and the TUBB3-positive cells in the ganglion cell layer were counted." (PMID 23806181, 2013).
Hypoglycemia (2 papers, 2013 to 2020). A decreased concentration of glucose in the blood. "Hypoxia and poor nutritional status, such as hypoglycemia, have been suggested as important causes of enhanced TUBB3 expression." (PMID 33256003, 2020). "What is more, these data support the notion that miR-200c interacted with the TUBB3 3′UTR in hypoglycemia and that such an interaction was important for HuR binding and increased expression of TUBB3 under stressing conditions." (PMID 23394580, 2013). "The HuR silencing by transient transfection in A2780 cells reverted the induction of TUBB3 expression in hypoglycemia, while in the OVCAR-3 and OV2774 cells the decrease of TUBB3 expression is detectable also in basal conditions." (PMID 23394580, 2013).
hypopharyngeal cancer (2 papers, 2022 to 2023). Carcinoma, predominantly squamous cell, arising from the epithelial cells of the hypopharynx. "A study performed immunohistochemical staining on 667 cases of oral cancer, hypopharyngeal cancer, and LSCC tissues to detect the expression of TUBB3." (PMID 35945754, 2022).
lymph node metastasis (2 papers, 2017 to 2020). "High TUBB3 expression is associated with adverse prognosis, including advanced tumor stage, lymph node metastasis and minor response to neoadjuvant therapy." (PMID 29383151, 2017). "Our multivariate analysis revealed TUBB3 as an independent prognostic factor in the group of minor responders when jointly analyzed with lymph node metastasis." (PMID 29383151, 2017).
medulloblastoma (2 papers, 2018 to 2022). A malignant, invasive embryonal neoplasm arising from the cerebellum. "It has been found that TUBB3 was highly expressed in lung neuroendocrine carcinoma and medulloblastoma, which was associated with positive lymphatic permeation." (PMID 35847907, 2022). "High expression of MRP1 (89%, 8/9 tumors), TUBB3 (86%, 18/21 tumors), PTEN (85%, 28/33 tumors), TOP2A (84%, 26/31 tumors), thymidylate synthase (TS; 80%, 24/30 tumors), RRM1 (71%, 15/21 tumors), and TOP1 (63%, 19/30 tumors) were found in medulloblastoma." (PMID 29869738, 2018).
Moebius syndrome (2 papers, 2020 to 2021). Moebius syndrome is a very rare congenital cranial dysinnervation disorder characterized by complete or incomplete facial paralysis in association with bilateral palsy of the abducens nerve causing impairment of ocular abduction. "Subjects with TUBB3 R262H syndrome received a variety of other diagnoses prior to their genetic diagnosis, including Moebius syndrome, Cary-Fineman-Ziter syndrome, and Marden Walker syndrome, all of which have some overlapping features with TUBB3 R262H." (PMID 34652576, 2021).
Nystagmus (2 papers, 2021 to 2024). Rhythmic, involuntary oscillations of one or both eyes related to abnormality in fixation, conjugate gaze, or vestibular mechanisms. "In a previous report, nystagmus was present in patients with TUBB3 mutations; however, in our patients, nystagmus was present not only in patients with TUBB3 mutations, but also in patients with KIF21A mutations." (PMID 39148141, 2024). "Herein, we report a case of c.967A>G:p.(M323V) variant in the TUBB3 gene found in a male infant who had only infantile nystagmus without CFEOM." (PMID 33921132, 2021). "In a previous study, the heterozygous c.967A>G:p.(M323V) TUBB3 variant caused nystagmus phenotypes without CFEOM in two patients in the same family (father and son)." (PMID 33921132, 2021). "We also thought that TUBB3 and TUBA1A genes should be included in the targeted panel of infantile nystagmus." (PMID 33921132, 2021).
optic nerve hypoplasia (2 papers, 2021). "However, using MRI studies, optic nerve hypoplasia has previously been described in patients with KIF21A mutations and TUBB3 mutations." (PMID 33806565, 2021).
papillary carcinoma (2 papers, 2020 to 2022). A malignant epithelial neoplasm characterized by a papillary growth pattern. "IHC revealed that the levels of TUBB3 were higher in conventional papillary carcinomas (cPTCs) and anaplastic thyroid carcinomas (ATCs)." (PMID 33256003, 2020).
prostate adenocarcinoma (2 papers, 2017 to 2021). "A widely used pan‐neuronal marker notwithstanding, TUBB3 expression was not related to neuroendocrine differentiation (NED, defined as positivity of generic NE markers chromogranin A and synaptophysin) in conventional prostate adenocarcinoma (p = 0.653)." (PMID 34318630, 2021).
small cell lung carcinoma (2 papers, 2014 to 2022). Small cell lung cancer (SCLC) is a highly aggressive malignant neoplasm, accounting for 10-15% of lung cancer cases, characterized byrapid growth, and early metastasis. "To date, there is little data on TUBB3 expression in small cell lung carcinoma (SCLC)." (PMID 24396456, 2014).
thyroid cancer (2 papers, 2020 to 2022). "High TUBB3 expression in thyroid cancer cells correlated with positivity to BRAF mutation-specific antibody." (PMID 33256003, 2020). "Very few attempts have been made to investigate TUBB3 expression and its prognostic impact in thyroid cancer, except for one study reporting the association between TUBB3 and taxane resistance in ATC." (PMID 33256003, 2020). "Our results suggest that high expression of TUBB3 in thyroid carcinoma could predict invasive potential and possibly be linked with epithelial–mesenchymal transition." (PMID 33256003, 2020). "Although we identified complex patterns of AS of the TUBB3 gene, leading to a possible loss of its expression due to NMD in PTC, the roles of these patterns in tumorigenesis in thyroid cancers and the clinical implications remain to be further elucidated." (PMID 35277656, 2022). "In conclusion, the present study is so far the first to show the role of TUBB3 in the pathogenesis of thyroid cancer." (PMID 33256003, 2020). "In our study, we observed EMT-related morphological changes, including tumor budding, in TUBB3-positive cells and found that migration and invasion were more active in thyroid cancer cells with high TUBB3 expression." (PMID 33256003, 2020). "Immunohistochemistry (IHC) for TUBB3 and E-cadherin was performed on a total of 254 cases of thyroid cancer specimens." (PMID 33256003, 2020). "We suggest that overexpression of TUBB3 can be induced during the stromal invasion of thyroid carcinoma and is an adverse prognostic marker." (PMID 33256003, 2020). "We aim to evaluate the clinicopathologic significance of TUBB3 and its potential role as a therapeutic target in thyroid carcinoma." (PMID 33256003, 2020). "In this study, we comprehensively investigated the expression of TUBB3 in various types of thyroid carcinomas, including the newly emerging entity “noninvasive follicular thyroid neoplasm with papillary-like nuclear features (NIFTP)”." (PMID 33256003, 2020). "In this study, we aim to evaluate the prognostic value of class III beta-tubulin (TUBB3) and uncover the relationship between TUBB3 and invasive potential in thyroid carcinoma." (PMID 33256003, 2020). "In thyroid carcinoma, TUBB3 and ECAD showed different expression patterns according to histologic subtypes." (PMID 33256003, 2020). "To date, there have been few studies exploring the role of TUBB3 in thyroid cancer." (PMID 33256003, 2020). "TUBB3 expression in thyroid carcinoma might occur with a tight connection with certain environmental stimuli and stromal interactions." (PMID 33256003, 2020).
anaplastic large cell lymphoma (1 paper, 2021). Anaplastic large cell lymphoma (ALCL) is a rare and aggressive peripheral T-cell non-Hodgkin lymphoma, belonging to the group of CD30-positive lymphoproliferative disorders, which affects lymph nodes and extranodal sites. "Investigation of the expression of FDC markers in HL and anaplastic large cell lymphoma (ALCL) revealed GLI3, fascin (actin-bundling protein found in membrane ruffles), and TUBB3 (a member of the beta-tubulin protein family) as the most sensitive markers, which were diffusely positive in HL." (PMID 33494284, 2021).
Apert syndrome (1 paper, 2025). Apert syndrome (AS) is a frequent form of acrocephalosyndactyly, a group of inherited congenital malformation disorders, characterized by craniosynostosis, midface hypoplasia, and finger and toe anomalies and/or syndactyly. "Calvaria of P0 Fgfr2+/P253R Apert syndrome mice and their unaffected littermates (Fgfr2+/+) were stained with TUBB3, CD31, and Emcn and imaged with our QLSM workflow." (PMID 39984434, 2025).
autonomic dysfunction (1 paper, 2021). "While it has not been established whether these findings are caused by the TUBB3 variants, together they raise the possibility that cardiac conduction problems are related to the TUBB3 peripheral neuropathy or autonomic dysfunction." (PMID 34652576, 2021).
Cerebellar dysplasia (1 paper, 2022). Cerebellar dysplasia (abnormal growth or development) is defined by abnormal cerebellar foliation, white matter arborization, and gray-white matter junction. "Furthermore, we also noted that TUBB3 R380C variant had been reported in patients diagnosed with “neurodevelopmental disabilities” and “cerebellar dysplasia (CD)”, however the ocular manifestations of the patients were not described clearly by authors." (PMID 36494820, 2022).
cervical cancer (1 paper, 2022). A primary or metastatic malignant neoplasm involving the cervix. "Experimental studies indicated that the biological effects exerted by ERCC1 in cervical cancer might be mediated by its associated genes and affected signaling pathways (i.e., XPF, TUBB3, and." (PMID 36713431, 2022).
COVID-19 (1 paper, 2023). A disease caused by infection with severe acute respiratory syndrome coronavirus 2. "Among them, six genes (CXCR4, ENO1, FASN, GATA6, PDK1 and TUBB3) have been reported to be associated with the pathological mechanism of COVID-19 and OA." (PMID 37291167, 2023). "ENO1 and TUBB3 were found to be probably related to the progression of OA, while FASN and GATA6 may participate in COVID-19." (PMID 37291167, 2023).
Crohn disease (1 paper, 2021). A gastrointestinal disorder characterized by chronic inflammation involving all layers of the intestinal wall, noncaseating granulomas affecting the intestinal wall and regional lymph nodes, and transmural fibrosis. "Finally, staining inflamed and non-inflamed tissues from UC and Crohn’s disease (CD) patients revealed an increased positivity for TUBB3 in inflamed mucosal tissues compared with non-inflamed tissues." (PMID 34571902, 2021).
ependymoma (1 paper, 2018). A WHO grade II, slow growing tumor of children and young adults, usually located intraventricularly. "This ependymoma cohort showed minimal alterations in gene amplifications and mutations but had high expression rates of DNA synthesis and repair enzymes such as RRM1 (47%), ERCC1 (48%), TOPO1 (62%) and class III β-tublin (TUBB3) (57%), which are also all associated with chemoresistance." (PMID 29487694, 2018). "Notably, ependymomas frequently overexpressed proteins implicated in DNA synthesis, transcription, and repair and/or drug resistance, including BCRP (5/7 [71%]), RRM1 (14/30 [47%]), ERCC1 (13/25 [48%]), TUBB3 (12/21 [57%]), TOPO1 (23/37 [62%]), and MRP1 (8/14 [43%])." (PMID 29487694, 2018).
esophageal squamous cell carcinoma (1 paper, 2014). Esophageal squamous cell carcinoma (ESCC) is a type of esophageal carcinoma (EC) that can affect any part of the esophagus, but is usually located in the upper or middle third. "However, to the best of our knowledge no study has been conducted using ERCC1, TYMS, TUBB3, RRM1 and TOP2A simultaneously in esophageal squamous cell carcinoma (ESCC)." (PMID 24926347, 2014).
Ewing sarcoma (1 paper, 2017). A small round cell tumor that lacks morphologic, immunohistochemical, and electron microscopic evidence of neuroectodermal differentiation. "High AR expression could present as a potential therapeutic target for DSRCT while taxanes may be more effective in Ewing sarcoma compared to DSRCT based on TUBB3 expression." (PMID 29225486, 2017).
eye movement disorders (1 paper, 2021). "Heterozygous missense variants in TUBB3 cause a wide variety of phenotypes, ranging from lethal cortical malformations to isolated eye movement disorders, with very clear genotype-phenotype correlations." (PMID 34652576, 2021).